RMRP (RNA component of mitochondrial RNA processing endoribonuclease)
Synonyms: RMRPR; RRP2; NME1; CHH
Gene: Gene (Ensembl biotype ribozyme) on chromosome 9 (35,657,750 to 35,658,019, reverse strand). Ensembl gene ENSG00000277027.
Gene Ontology:
Molecular function: ribonuclease MRP activity
Biological process: rRNA processing
Cellular component: ribonuclease MRP complex
Gene-disease validity (ClinGen):
ClinGen rates the evidence that RMRP causes each of these diseases.
cartilage-hair hypoplasia (autosomal recessive): Definitive. Cartilage-hair hypoplasia is a disease affecting the bone metaphyses causing small stature from birth.
Diseases named in the same sentence as RMRP in open-access papers:
RMRP is named in the same sentence as 65 diseases in open-access papers, as found by Europe PMC text mining. Sharing a sentence is not in itself a finding about the gene and the disease. The quoted sentences say what the papers report.
cartilage-hair hypoplasia (19 papers, 2011 to 2026). "Among these there were two SNVs located in noncoding regions (GM79, RMRP, associated with cartilage-hair hypoplasia and GM275, HSD17B4, associated with Perrault syndrome)." (PMID 38909121, 2024). "In humans, mutations in the RMRP gene has been associated with cartilage-hair hypoplasia (CHH) syndrome, a multi-systemic disorder that is inherited via an autosomal recessive mode." (PMID 33996836, 2021). "RMRP was originally identified as a causative gene for cartilage-hair hypoplasia, because numerous mutations in the RMRP gene caused the disease by affecting multiple organ systems." (PMID 34621748, 2021). "Mutation of RMRP was identified in patients with cartilage-hair hypoplasia, a human ribosomopathy characterized by metaphyseal dysplasia, anemia, and immune dysregulation." (PMID 34621748, 2021). "Germ-line point-mutations, insertions, and duplications reducing RMRP expression cause the recessively inherited disorder “cartilage-hair hypoplasia” (CHH), which is primarily associated with abnormalities in bone and cartilage development." (PMID 33329688, 2020). "Cartilage hair hypoplasia (CHH) is an autosomal recessive disorder due to mutations of the non-coding RMRP gene, whose transcript is involved in ribosomal RNA processing, mitochondrial DNA replication, and regulation of target gene transcription." (PMID 31440487, 2019). "Mutations in RMRP have been detected in individuals afflicted with Cartilage Hair Hypoplasia (CHH), a syndrome characterized by short stature, sparse hair, immunodeficiency and in a subset of patients severe combined immunodeficiency or life threatening anemia." (PMID 22039455, 2011). "Cartilage-hair hypoplasia syndrome (CHH) is an autosomal recessive disorder frequently linked to n.72A>G (previously known as n.70A>G and n.71A>G), the most common RMRP variant worldwide." (PMID 38862721, 2024). "Biallelic mutations in the non-coding RNA gene RMRP cause Cartilage-hair hypoplasia (CHH), a rare skeletal dysplasia in which the main phenotypic characteristic is severe progressive growth retardation." (PMID 34956076, 2021). "Approximately 100 distinct mutations in RMRP that disrupt rRNA processing have been related to cartilage-hair hypoplasia (CHH) development, a form of dwarfism." (PMID 33419375, 2020). "BACKGROUND: Cartilage-hair hypoplasia (CHH), an autosomal recessive skeletal dysplasia due to RMRP mutations, is characterized by short stature, immunodeficiency, anemia, and increased malignancies." (PMID 42063088, 2026). "Cartilage-hair hypoplasia (CHH) is a rare autosomal recessive chondrodysplasia and an inborn error of immunity caused by a variant in the RMRP gene, which is the RNA component of mitochondrial RNA processing endoribonuclease." (PMID 37308912, 2023). "For example, cartilage hair hypoplasia (CHH), caused by mutations in the RMRP gene, which encodes an untranslated multifunctional RNA gene product, can manifest immune phenotypes that range from no significant impairment to T cell deficient typical SCID." (PMID 35967429, 2022). "It was shown that in patients affected by cartilage-hair hypoplasia (CHH), mutations in RMRP which is the RNA component of the ribonucleoprotein complex RNase MRP, upregulation of several cytokines and cell cycle regulatory genes are obvious." (PMID 31514268, 2019). "Cartilage-hair hypoplasia (CHH, OMIM #250250) is caused by mutations in RMRP, which encodes the long non-coding RNA component of mitochondrial RNA-processing endoribonuclease." (PMID 30410491, 2018). "An notable example is RMRP, a gene known to be involved in cartilage-hair hypoplasia (CHH), an autosomal recessive congenital disorder which is found across Europe but shows increased frequency in the Finnish and Old Order Amish populations." (PMID 40791678, 2025).
cartilage-hair hypoplasia (continued). "In cartilage-hair hypoplasia (CHH), an autosomal recessive hereditary condition, the RNA component of mitochondrial RNA processing endoribonuclease (RMRP), an lncRNA, was first found." (PMID 36793271, 2023).
Immunodeficiency (12 papers, 2011 to 2026). Failure of the immune system to protect the body adequately from infection, due to the absence or insufficiency of some component process or substance. "In summary, AK2 joins RAG1, ADA as well as ITCH and RMRP genes in the list of known causes of immune deficiency in the Amish population." (PMID 31673062, 2019). "Additional genetic defects in MTHFD1, RMRP, CORO1A, PNP, DOCK8, ATM, and BCL11B, among others also cause combined immunodeficiencies, which can be detected by low TREC copy number analysis." (PMID 29713328, 2018). "This clinical spectrum includes different degrees of short stature, hair hypoplasia, defective erythrogenesis, and immunodeficiency, and the mutant RMRP may affect both messenger RNA (mRNA) and ribosomal RNA (rRNA) cleavage and thus cell-cycle regulation and protein synthesis." (PMID 36140746, 2022).
lung carcinoma (8 papers, 2016 to 2021). "RMRP was reported to be upregulated in a wide range of human diseases, such as cardiac fibrosis, myocardial ischemia-reperfusion injury, and lung cancer." (PMID 34516335, 2021). "Increasing reports showed that many lncRNAs including RMRP, PVT1, HOTAIR, HIT, and TUG1 showed disease-associated dysregulation in lung cancer." (PMID 30154938, 2018). "Since RMRP was translocated to the cytoplasm for mitochondrial RNA processing activity, it was reported that the elevation in the expression of RMRP could promote the progression of diseases, such as lung Cancer, atherosclerosis and coronary heart disease." (PMID 34512545, 2021). "We have found that expression levels of SNHG1 and RMRP are reliably measured in plasma, and the lncRNAs may provide cell-free circulating biomarkers for lung cancer." (PMID 32294932, 2020). "Moreover, Meng et al35 demonstrated that the expression of RMRP was up‐regulated in lung cancer tissues and overexpression of RMRP enhanced lung cancer cell growth, invasion and colony formation through regulating miR‐206 expression." (PMID 30156374, 2018). "Droplet Digital PCR (ddPCR) was used for quantification of the genes (miRs-21, 210, 486-5p, SNHG1, RMRP, FUT8, and POFUT1) in plasma of a development cohort of 64 lung cancer patients and 33 cancer-free individuals." (PMID 29872497, 2018). "Our data proved that RMRP acted as an oncogene LncRNA to promote the expression of KRAS, FMNL2 and SOX9 by inhibiting miR-206 expression in lung cancer." (PMID 27906963, 2016).
bladder cancer (6 papers, 2022 to 2025). "Targeting lncRNAs, such as linc-ROR in pancreatic cancer and RMRP in bladder cancer, has led to a marked reduction in tumor volume and weight, as well as inhibited tumor metastasis in BALB/c nude mice or C57BL/6J male mice." (PMID 39925803, 2025). "Among them, RMRP was most significantly upregulated in patients with bladder cancer." (PMID 40075875, 2025). "Urinary exosomes from 42 bladder cancer patients were collected and quantified for seven lncRNAs (UCA1, H19, MALAT1, TUG1, GAS5, RMRP, and LINC01517), showing increased expression of RMRP, UCA1, and MALAT1 in bladder cancer patients." (PMID 40075875, 2025).
gastric cancer (6 papers, 2016 to 2022). A primary or metastatic malignant neoplasm involving the stomach. "In the xenograft model of gastric cancer, RMRP silencing attenuated tumor growth via modulation of miR-206 expression." (PMID 33996836, 2021). "RMRP silencing in gastric cancer cells suppresses cell proliferation via modulation of miR-206 and subsequent regulation of cell cycle transition through modulation of Cyclin D2." (PMID 33996836, 2021). "In other types of cancer, including gastric cancer and glioma, RMRP also exerts a promoting effect on tumors through different mechanisms." (PMID 30926681, 2019). "This information implies that RMRP is most likely to act as a reservoir for the production of some small RNAs to regulate the cell cycle in gastric cancer." (PMID 27192121, 2016). "RMRP inhibited the expression of miR-206 and regulated the cell cycle through modulating Cyclin D2 expression in gastric cancer cell." (PMID 27906963, 2016). "RMRP suppressed the expression of miR-206 and regulated the cell cycle by modulating Cyclin D2 expression in gastric cancer cell." (PMID 27906963, 2016). "Because the RNA component of mitochondrial RNA processing endoribonuclease (RMRP) is one of the dysregulated lncRNAs in gastric cancer, this study explored its molecular mechanisms in carcinogenesis." (PMID 27192121, 2016). "In this study, to clarify the potential roles of RMRP in gastric cancer and its clinical values, we first detected RMRP levels in tissue, plasma and gastric juice from patients with various stages of gastric tumorigenesis." (PMID 27192121, 2016). "Previous study showed that the expression of RMRP was deregulated in gastric cancer." (PMID 27906963, 2016). "We found that RMRP levels were downregulated in gastric cancer tissues." (PMID 27192121, 2016). "Our data showed that RMRP plays an important role in gastric cancer occurrence and development, and may be a potential novel biomarker for screening and predicting the prognosis of gastric cancer." (PMID 27192121, 2016).
lung adenocarcinoma (6 papers, 2016 to 2023). A carcinoma that arises from the lung and is characterized by the presence of malignant glandular epithelial cells. "ALKBH5 upregulates the expression of RMRP through demethylation, and the upregulation of RMRP promotes the proliferation and invasion of lung adenocarcinoma cells while inhibiting cell apoptosis." (PMID 38094306, 2023). "For example, in lung adenocarcinoma, the expression of RMRP is up-regulated and the ectopic expression of RMRP promotes the proliferation, colony formation, and invasion of cancer cells." (PMID 30926681, 2019). "In this study, we demonstrated that theexpression of RMRP was upregulated in lung adenocarcinoma tissues compared to the matched adjacent normal tissues." (PMID 27906963, 2016). "In line with this, we demonstrated that overexpression of RMRP suppressed miR-206 expression in lung adenocarcinoma cell." (PMID 27906963, 2016). "In conclusion, we demonstrated that RMPR expression was upregulated in lung adenocarcinoma tissues and overexpression of RMRP promoted lung adenocarcinoma cell proliferation, colony formation and invasion." (PMID 27906963, 2016). "In this study, we demonstrated that RMRP expression was upregulated in lung adenocarcinoma tissues compared to the matched adjacent normal tissues." (PMID 27906963, 2016). "RMRP expression was upregulated in the lung adenocarcinoma tissues compared to the matched adjacent normal tissues." (PMID 27906963, 2016). "We also showed that RMRP expression was upregulated in lung adenocarcinoma cell lines (A549, SPC-A1, H1299 and H23) compared to the bronchial epithelial cell line (16HBE)." (PMID 27906963, 2016). "In line with this, RMRP expression was upregulated in lung adenocarcinoma cell lines compared to the bronchial epithelial cell line." (PMID 27906963, 2016). "Also, cell proliferation, migration, and invasion are reduced and cell apoptosis is increased in RMRP-knocked down lung adenocarcinoma cell lines." (PMID 35534472, 2022). "Moreover, of 35 lung adenocarcinoma samples, RMRP was upregulated in 25 cases (25/35; 71.4%) compared to the adjacent normal tissues." (PMID 27906963, 2016). "Moreover, of 35 lung adenocarcinoma samples, RMRP expression was upregulated in 25 cases (25/35; 71.4%) compared to the adjacent normal tissues." (PMID 27906963, 2016). "Ectopic expression of RMRP promoted lung adenocarcinoma cell line H1299 cell proliferation." (PMID 27906963, 2016). "In addition, the RMRP expression was upregulated in lung adenocarcinoma cell lines (A549, SPC-A1, H1299 and H23) compared to the bronchial epithelial cell line (16HBE)." (PMID 27906963, 2016). "Moreover, ectopic expression of RMRP promoted lung adenocarcinoma cell proliferation, colony formation and invasion." (PMID 27906963, 2016). "Furthermore, RMRP exhibited an oncogenic activity through targeting miR-206 in lung adenocarcinoma cell." (PMID 27906963, 2016). "Therefore, RMRP might serve as a therapeutic target in lung adenocarcinoma." (PMID 27906963, 2016). "In our study, we also demonstrated that ectopic expression of RMRP promoted the expression of KRAS, FMNL2 and SOX9 in lung adenocarcinoma cell, which were the direct taget gene of miR-206." (PMID 27906963, 2016). "The findings indicate that the aberrant upregulation of RMRP is strictly related to the negative prognosis of patients with lung adenocarcinomas." (PMID 35534472, 2022). "The expression of RMRP was negative correlated with the expression of miR-206 in lung adenocarcinoma tissues." (PMID 27906963, 2016). "In addition, our data showed that ectopic expression of RMRP promoted theexpression of KRAS, FMNL2 and SOX9 in lung adenocarcinoma cell." (PMID 27906963, 2016). "ALKBH5 can upregulate RMRP through the demethylation of m6A, and the tumorigenesis can be proscribed by ALKBH5 knockdown in vitro and in vivo, representing that ALKBH5 may be directly correlated with RMRP function to modulate lung adenocarcinoma tumor cells." (PMID 35534472, 2022).
breast carcinoma (5 papers, 2015 to 2022). "In this study, we found that RMRP is amplified and overexpressed in numerous human cancers including breast cancer, and its high expression level is significantly associated with unfavorable cancer prognosis." (PMID 34621748, 2021). "We found that the RMRP gene is amplified and overexpressed in a variety of human cancers, and the high level of RMRP is significantly associated with poor prognosis of multiple cancers, including breast cancer." (PMID 34621748, 2021). "RMRP was recently found to play a role in cancer development, but its function and the underlying mechanism in breast cancer are largely unknown." (PMID 34621748, 2021). "In breast cancer, upregulation of RMRP partially resulted from its promoter mutation or Wnt/Hippo activation, but its biological function and the underlying mechanism in this cancer remain unclear." (PMID 34621748, 2021). "Here, we report that RMRP is amplified and highly expressed in various malignant cancers, and the high level of RMRP is significantly associated with their poor prognosis, including breast cancer." (PMID 34621748, 2021). "Recently, it was reported that recurrent mutations in the RMRP promoter are associated with higher expression level of RMRP in breast cancer, suggesting that this lncRNA may play a role in breast carcinogenesis." (PMID 34621748, 2021). "Besides CHH, several cancer-genome studies have revealed RMRP SCNAs due to focal amplifications, and the RMRP promoter was found to contain a breast-cancer associated mutation hotspot, impacting RMRP transcription." (PMID 33329688, 2020). "To validate this result, we determined if RMRP regulates the mRNA expression of AKT by RT-qPCR in breast cancer cells." (PMID 34621748, 2021). "Finally, we determined if RMRP promotes breast cancer cell growth and migration through activation of the AKT pathway." (PMID 34621748, 2021). "Furthermore, we found that ectopic expression of RMRP dramatically promotes, while depletion of RMRP prohibits, breast cancer cell migration." (PMID 34621748, 2021). "Interestingly, enhanced level of RMRP was correlated with that of β-catenin mRNA in breast cancer tumor tissues." (PMID 26415221, 2015). "Thus, our finding has emphasized the important role of RMRP by activating AKT in breast cancer." (PMID 34621748, 2021). "Remarkably, RMRP endorses breast cancer progression in an AKT-dependent fashion, as knockdown of AKT completely abolishes RMRP-induced cancer cell growth and migration." (PMID 34621748, 2021). "Although recent studies suggested a potential role of RMRP in regulating AKT in the ischemic models, our study demonstrates for the first time that RMRP can promote breast cancer cell growth and migration via AKT activation." (PMID 34621748, 2021). "Collectively, these results demonstrate that RMRP can activate the AKT signaling pathway, which might account for its tumor-promoting functions in breast cancer cells." (PMID 34621748, 2021). "Consistently, ectopic RMRP dramatically increased the level of AKT protein as well as its phosphorylated form in JIMT-1 and BT549 cells, while knockout or knockdown of RMRP resulted in the significant reduction of AKT and phosphorylated AKT in both breast cancer cell lines." (PMID 34621748, 2021).